IL6 (interleukin 6)
Diseases named in the same sentence as IL6 in open-access papers (continued):
Sharing a sentence is not in itself a finding about the gene and the disease.
ovarian carcinoma (continued). "This suggests that IL-6 might be a potential target for treatment in women with advanced ovarian cancer." (PMID 39125732, 2024). "Our results suggest that increase in IL-6 expression levels by ovarian cancer may lead to kidney inflammation and its reversal by WFA." (PMID 39394174, 2024). "However, IL-6 also enhances ovarian cancer cell proliferation, migration, invasion, and drug resistance while inhibiting apoptosis." (PMID 39061859, 2024). "Overall, these studies have shown little promise for the utility of IL-6 pathway inhibition as a standalone treatment for ovarian cancer, while supporting the possibility that combination regimens may be a fertile area for future investigation." (PMID 38689325, 2024). "The tumor-associated stroma, which includes mesothelial cells, fibroblasts, and adipocytes, serves as a reservoir for IL-6 and contributes to the establishment of favorable niches for tumor cell growth, and chemotherapeutic resistance, and the maintenance of OCSCs (ovarian cancer stem cells)." (PMID 38575576, 2024). "The concentration of Il-6 was higher in advanced stages of ovarian cancer, so it may be a clinically reliable marker for differentiation of high-grade ovarian cancer and patients with normal ovaries." (PMID 37373969, 2023). "Moreover, STAT3 shRNA decreased the expression of IL-6 in ovarian cancer cells in vitro and the ovarian xenograft tumor model." (PMID 38067351, 2023). "It revealed that Il-6 is a more predictable marker of diagnosis of ovarian cancer with age, CA125, HE4, ROMA, WBC, hemoglobin, number of platelets, C-reactive protein, procalcitonin and NLR (neutrophil-to-lymphocyte ratio) and PLR (platelet-to-lymphocyte ratio)." (PMID 37373969, 2023). "CCL2 from mesenchymal stromal cells acts on ovarian cancer cells and induces IL-6 secretion." (PMID 37445830, 2023). "The mechanism of Il-6 is highly activated in various neoplastic diseases such as breast cancer, pancreatic cancer, digestive cancers (gastric, colon, colorectal), lung and ovarian cancer." (PMID 37373969, 2023). "However, the mean level of Il-6 of advanced stages of ovarian cancer was also higher than in earlier ones." (PMID 37373969, 2023). "Elevation of IL6 levels may result from ovarian cancer cell proliferation via the activation MAPK-ERK-Akt (protein kinase B) signaling pathway." (PMID 37792745, 2023). "IL-6 can be secreted in ascites by ovarian cancer cells and tumor microenvironment cells." (PMID 37175439, 2023). "Following primary treatment for epithelial ovarian cancer, diurnal cortisol rhythms normalized and IL-6 decreased, suggesting inflammation markers may re-regulate following treatment." (PMID 37746277, 2023). "Additionally, it has been noted that protein kinase C (PKC), Akt, lysophosphatidyl acid (LPA), and interleukin-6 (IL-6) are increased in ovarian cancer." (PMID 36903316, 2023). "Taken together, our findings demonstrate that RV can counteract IL-6-promoted ovarian cancer progression by rescuing glycolysis-mediated inhibition of autophagy and support the view that targeting Warburg metabolism can be an effective strategy to limit the risk for cancer metastasis." (PMID 36675246, 2023). "Furthermore, producing MMPs in ovarian cancer cells by IL6 can enhance invasive and tumorigenesis performance The increase of IL6 levels in peritoneum fluid has also shown that the role of JAK-STAT helps the invasive process of ovarian cancer." (PMID 37792745, 2023).
ovarian carcinoma (continued). "Additionally, the production of IL6 by M2 macrophage can induce cancer cellular proliferation via STAT3 activation in ascites patients with advanced ovarian cancer." (PMID 37792745, 2023). "IL-6 is abundant in the ascitic liquid of ovarian cancer patients, and promotes cell cycle progression and growth as well as increases the invasive phenotype of ovarian cancer." (PMID 36675246, 2023). "Therefore, it has been proposed that IL-6 is a central cytokine that promotes ovarian cancer progression, although its exact role during disease development has not been well established." (PMID 38141599, 2023). "In ovarian cancer, IL-6 is believed to be involved in host immune responses to the disease." (PMID 37175439, 2023). "To confirm that IL-6 enhancement of ovarian cancer cell migration depends on glucose metabolism, we performed a wound healing scratch assay in the presence of 2-deoxy-D-glucose (2-DG) or sodium oxamate, which inhibit upstream and downstream the glycolytic pathway, respectively." (PMID 36675246, 2023). "Furthermore, cisplatin-sensitive OV2008 and A2780 ovarian cancer cell lines treated with IL-6, which activates STAT3, showed increased cisplatin resistance." (PMID 38067351, 2023). "Based on our findings, we can conclude that butein from Butea monosperma flower isolates inhibits ovarian cancer growth by binding to IL-6 and suppressing its activity, which results in inactivation of STAT3 and nuclear accumulation of FoxO3a and p27kip1, thereby limiting tumor growth." (PMID 37047012, 2023). "The inverse correlation between the mRNA and protein levels of TNF-α and IL-6 has been reported in ovarian cancer cells by Israelsson and colleagues, which is possibly due to the complex regulatory mechanisms governing gene transcription, protein translation, and the stability of these cytokines." (PMID 38139181, 2023). "Il-6 can be a prognostic marker of advanced stages of ovarian cancer and neoplastic diseases." (PMID 37373969, 2023). "However, IL-6 has also been found to enhance anti-angiogenic therapy in certain diseases, such as ovarian cancer, by suppressing ANG-1 expression and promoting dependence on VEGF for angiogenesis." (PMID 36344987, 2022). "The potential of IL-6 to enhance tumor growth and progression by autocrine and paracrine effects and to produce particular immunological and metabolism changes that influence prognosis has been convincingly shown in ovarian cancer." (PMID 36386196, 2022). "IL-6 is a key stimulatory cytokine found in the milieu of ovarian cancer, and IL-6 inhibitors may be used to treat the disease." (PMID 36386196, 2022). "Furthermore, we postulate that letrozole blocks estrogen synthesis to decrease estrogen signaling and break the feed-forward loop between estrogen and IL6/LIF cytokine signaling in the ovarian cancer tumor microenvironment." (PMID 36230597, 2022). "Elevated IL-6 levels are characteristic of ovarian cancer, gastric cancer and esophageal cancer." (PMID 35735559, 2022). "Furthermore, IL6 has been shown to regulate and enrich ovarian cancer stemness following platinum-based therapy." (PMID 36230597, 2022). "Cancerous cells release IL-6 within the ovarian cancer microenvironment, resulting in limitation of dendritic cell maturation and promoting immunosuppressive classically activated tumor-associated macrophages (TAMs), compromising the stimulation of tumor-infiltrating T cells." (PMID 36386196, 2022). "Therefore, we sought to characterize the impact of IL6/LIF signaling on estrogen signaling in epithelial ovarian cancer and investigate the efficacy of combination therapy." (PMID 36230597, 2022). "However, the authors found that the ovarian cancer stroma from patients with routine metformin administration exhibited lower IL-6 expression." (PMID 36361682, 2022).
ovarian carcinoma (continued). "In concordance to this, we have previously shown IL6 can drive destabilized vasculature with loss of pericytes via activation of the ANG2 signaling and that anti-IL6 therapy can normalize this effect in xenograft models of ovarian cancer." (PMID 35313341, 2022). "IL-6 upregulates the expression of multidrug resistance gene 1 (MDR-1) and glutathione transferase (GST-π), thus facilitating drug efflux which is regarded as an important cause of multidrug resistance (MDR) development in ovarian cancer." (PMID 36359776, 2022). "Therefore, further studies are needed to clarify the roles of IL-6 and IL-6R in ovarian cancer pathogenesis and treatment responses." (PMID 35681617, 2022). "Moreover, dual anti-ActRIIA/IIB antibody treatment reduced serum levels of IL-6 and reversed cachexia in mice, supporting a functional link between activin A and IL-6 signaling pathways observed in ovarian cancer cells." (PMID 35994202, 2022). "Subsequent analysis showed increased levels of IL-6 in ovarian cancer patient ascites, and treatment using anti-IL-6 antibodies showed decreased invasion and migration, decreased mesenchymal phenotype, and decreased activation of the JAK/STAT3 downstream signalling." (PMID 36429126, 2022). "IL-6 also enhances the migration capacity of SKOV3 ovarian cancer cells." (PMID 34440886, 2021). "These events are similar to those observed in advanced ovarian cancer which share similar pathogenesis mediated primarily by Interleukin-6, which is, as well demonstrated in ovarian cancer, the key cytokine driving the immunopathology, related systemic symptoms, and patient prognosis." (PMID 33550983, 2021). "The inflammatory response is also inversely related to leptin levels that, together with IL-6, may be a useful prognostic marker of disease outcome as demonstrated by us in a population of advanced ovarian cancer." (PMID 33809200, 2021). "In view of the proinflammatory nature of interleukin 6, this may indicate that the inflammatory process plays an important role in the pathogenesis of both ovarian cancer and benign ovarian cysts." (PMID 34573967, 2021). "In the meantime, TAMs as well as IFN-γ, TNF-α, IL-10 and especially IL-6 secreted by TAMs induced the expression of PD-L1 both in the cell membrane and in the cytoplasm of ovarian cancer cells, which inhibited the function of CD8+ T cells and promoted tumor growth." (PMID 34717710, 2021). "Similarly, we examined the effects of IL-6 in patients with advanced cancer, particularly ovarian cancer, and found that its deleterious effects must be counteracted at all stages of metastatic neoplastic disease." (PMID 33550983, 2021). "IL-8, together with IL-6, participates in the paracrine mechanism of expression regulation of the epithelial cell adhesion molecule (EpCAM), which contributes to tumor growth and whose overexpression occurs in ovarian cancer cells." (PMID 34572929, 2021). "In particular, in patients with advanced ovarian cancer, rising IL-6 levels were inversely related with a decreased BMI, body weight, and lean body mass, and were also associated with a progressive decrease in leptin levels with the lowest values observed near the time of death." (PMID 33809200, 2021). "IL-6 is another protein detected in the course of cancer, including ovarian cancer." (PMID 34572929, 2021). "Similarly, autocrine and paracrine signaling pathways stimulated by Interleukin-6, encoded by IL6, were shown to be associated with cancer cell proliferation, migration, stemness, and therapy resistance in ovarian cancer." (PMID 34439877, 2021). "In addition, IL-6 also enhanced the chemoresistance of ovarian cancer cells against cisplatin through the IL-6/STAT3/HIF-1α loop in vitro and in vivo." (PMID 33868231, 2021).
ovarian carcinoma (continued). "IL-6 is a pleiotropic cytokine that critically influences immune responses, inflammation, and haematopoiesis, and is expressed by multiple types of tumor tissue, such as those of breast, prostate, colorectal, and ovarian cancer." (PMID 34361836, 2021). "LIF is not always the sole cause, though, as in ovarian cancer IL-6 and LIF work together to stimulate STAT3 phosphorylation and stemness, while the loss of either LIF or IL-6 highly abrogates this process." (PMID 34395259, 2021). "Of note, the increase in the expression of IL-6, another M2b marker that can promote tumor growth and ascites formation in ovarian cancer, may explain the acceleration of ascites development in CpG-ODN/anti-PD-1 antibody-treated mice." (PMID 34439233, 2021). "For instance, high levels of IL-6 promoted the progression of malignant ascites in ovarian cancer." (PMID 34369236, 2021). "IL-6 is one of the most important mediators of ADSC effects on ovarian cancer." (PMID 34440886, 2021). "For example, inhibition of interleukin 6 (IL-6) was found to facilitate therapeutic activity when the anti-IL-6 antibody siltuximab was taken in clinical trials of patients with platinum-resistant ovarian cancer." (PMID 34857007, 2021). "In our previous studies we found that RV could revert the pro-migratory effect of stromal IL-6 on ovarian cancer and cholangiocarcinoma cells by rescuing autophagy from inhibition." (PMID 34831435, 2021). "Moreover, the authors also showed that both in ovarian cancer animal model and in patients with ovarian cancer, blocking IL-6 production with small interfering RNA or siltuximab, an anti-IL-6 antibody, respectively, normalized platelet counts." (PMID 33550983, 2021). "Interestingly, we detected significantly higher accumulation of IL-6 in the PF samples from patients with grade 3 of ovarian cancer than those with grade 2 (p < 0.001)." (PMID 33062717, 2020). "Thus, further investigation is required to explore the possibility of combining anti-IL-6 and EVs from ovarian cancer cells in a therapeutic approach." (PMID 32927431, 2020). "Elevated serum IL-6 levels in ovarian cancer patients, therefore, correlate with poor prognosis." (PMID 31979221, 2020). "Through scanning the cytokine benefits for angiogenesis, we found that At-EE treatment could significantly decrease ovarian cancer cell-secreted IL-6 and VEGF." (PMID 32190078, 2020). "Furthermore, IL-6 inhibits the apoptosis of ovarian cancer cells contributing to tumor growth and induces vascular endothelial growth factor- (VEGF-) mediated angiogenesis." (PMID 33062717, 2020). "Furthermore, we screened all six cell lines for endogenous interleukin-6 (IL-6) formation, as IL-6 treatment of A2780 ovarian cancer cells was shown to induce platinum resistance." (PMID 31979221, 2020). "Moreover, it has been shown that knockdown of STAT3 in macrophages that were co-cultured with SKOV3 human ovarian cancer cells inhibited cell proliferation of SKOV3 through the downregulation of IL-6 and IL-10 of macrophages." (PMID 32283687, 2020). "In line with results from ovarian cancer, IL-6 seems to be a promising candidate biomarker." (PMID 32759686, 2020). "The HATMSC2-MVs inhibit the activity of IL-6, and in conjunction with a decreased level of IL-8, may exert suppressive effects on the ovarian cancer cell line." (PMID 33266317, 2020). "Stimulating ovarian cancer cells with IL-6 promotes STAT3 phosphorylation and cell migration." (PMID 31949487, 2020). "We also assessed the usefulness of IL-6 in helping to discriminate ovarian cancer patients." (PMID 32042020, 2020). "Excessive IL-6 production promotes tumorigenesis (in breast, prostate, lung, colon, ovarian cancer), in this respect, to prevent cancer progression, a pharmacological modulation of IL-6 gene expression levels may have therapeutic benefits in human." (PMID 32178382, 2020).
ovarian carcinoma (continued). "Moreover, the upregulated miR-21 was packed into EVs, secreted by ovarian cancer which stimulated the secretion of IL-6 in M2 macrophage." (PMID 32927431, 2020). "Inclusion of early stages of epithelial ovarian cancer and comparison with benign masses and normal ovaries in a larger stage-stratified cohort will be required to ascertain the role of IL6 in generalized ovarian cancer screening including multiple and earlier disease stages." (PMID 32042020, 2020). "And IL-6/IL-6R axis is a potential target for ovarian cancer therapy." (PMID 32190078, 2020). "The concentrations of IL-6 both in the patients with ovarian cancer and in the patients with benign ovarian tumors were significantly higher (p < 0.0001) in the peritoneal fluid than in the plasma (median 4198.18 vs. 21.72 pg/ml and 56.55 vs. 13.65 pg/ml, respectively)." (PMID 33062717, 2020). "Based on the findings presented above, we next set out to determine whether SNHG12 played a role in ovarian cancer cell immune escape, mediated by the IL-6/miR-21 feedback loop." (PMID 32927431, 2020). "In early stage ovarian cancer, the fall in serum albumin likely results from metabolic factors secreted by ovarian cells, including interleukin-6 (IL-6), an inflammatory cytokine that inhibits the synthesis of albumin by hepatocytes and promotes the metastasis of ovarian cancer cells." (PMID 32723677, 2020). "These pieces of evidences demonstrated VEGF and IL-6 secreted by ovarian cancer cells were the key factors for angiogenesis, and At-EE could inhibit them." (PMID 32190078, 2020). "When elevated, IL-6 within the ascites of ovarian cancer patients correlates with poor outcomes." (PMID 31409361, 2019). "The observed cytokine reaction could explain the increase in mMDSC, since IL-6 is a known inducer of mMDSC expansion in humans and IL-1b correlates with mMDSC in blood of ovarian cancer patients." (PMID 31214202, 2019). "Mechanistically, LL-37 stimulates MSCs to secrete larger amounts of inflammatory and pro-angiogenic factors, such as IL-1 receptor antagonist, IL-6, IL-10, CCL5, VEGF, and MMP-2, and this phenomenon is closely associated with the promotion of ovarian cancer progression and metastasis." (PMID 30568223, 2019). "Previous reports have used combined inhibition of activated STAT signaling pathways and IL-6 as a therapeutic approach against drug-resistant cells, and other studies have shown that Taxol resistance in ovarian cancer can be overcome by inhibiting IL-6 and STAT3." (PMID 31601188, 2019). "Similarly, some studies about ovarian cancer have found that IL-6 also promotes the development of tumor, which is closely related to the prognosis." (PMID 31766991, 2019). "Several of these proteins have been described in the literature as mediators of ovarian cancer progression, including associations of their expression in tumor tissue or blood or ascites levels with ovarian cancer survival, for instance IL-6, GDF15, OPN/SST1, PVRL4, and VEGFA." (PMID 31737572, 2019). "In addition, IL-6 blockade in combination with paclitaxel had a synergistic effect on reducing tumor growth in murine models of epithelial ovarian cancer." (PMID 31337034, 2019). "Furthermore, they demonstrated pretreatment with the well-known diabetes drug metformin arrested stromal NFκB/IL6 activation and lessened the chemoresistance response in ovarian cancer cells." (PMID 31409361, 2019). "In turn, CAF-derived p38-regulated cytokines and chemokines, such as IL-6, CXCL10, and CCL5, mobilize glycogen that is associated with fueling glycolysis in cancer cells, increasing proliferation, invasion, and metastasis of ovarian cancer." (PMID 30568223, 2019). "Indeed, results from in vivo models show that neutralizing IL-6 enhances the therapeutic effect of paclitaxel in an ovarian cancer mouse model, leading to reduced tumor growth and angiogenesis." (PMID 29930760, 2018). "IL6 is an important cytokine in the ovarian cancer cytokine network." (PMID 29455640, 2018).